EIF4A1P5 (eukaryotic translation initiation factor 4A1 pseudogene 5)
Gene: Processed pseudogene on chromosome 13 (36,938,400 to 36,939,494, reverse strand). Ensembl gene ENSG00000226161.
Diseases named in the same sentence as EIF4A1P5 in open-access papers:
EIF4A1P5 is named in the same sentence as 1 disease in open-access papers, as found by Europe PMC text mining. Sharing a sentence is not in itself a finding about the gene and the disease. The quoted sentences say what the papers report.
lung carcinoma (1 paper, 2025). "Finally, EIF4A1P5 is an initiation factor in the 43 ribosome that assists with cytoplasmic translation and is found to have oncogenic properties in lung cancers." (PMID 41347211, 2025).